PCNA (proliferating cell nuclear antigen)
Diseases named in the same sentence as PCNA in open-access papers (continued):
Sharing a sentence is not in itself a finding about the gene and the disease.
tumor (continued). "The expression level of Ki67 and PCNA in oe-ZNF750 and sh-ZNF750 groups was in consistent with the observation results from the tumor growth." (PMID 35003347, 2021). "The SUMOylation of PCNA by SUMO2 is induced by the RNA polymerase II (RNAPII)-bound helicase RECQ5, which suppresses transcription-related DSB and functions as a tumor suppressor 93-97." (PMID 34671219, 2021). "Then we performed histological analysis (HE, PCNA and TUNEL staining) to further assess the anti-tumor ability of ZBTB28 in vivo." (PMID 33931087, 2021). "The expression levels of tumor progression-related proteins (MMP9, PCNA, and IL-1β) and MDSCs' proliferation and activation-related proteins (COX2 and PDL1) were significantly downregulated." (PMID 34055197, 2021). "Compared to control group, tumor xenograft generated from TRIM37 overexpression cells displayed significantly enhancive Ki67 and PCNA expression, upregulation of ub-H2A and TGF-β1 levels were also observed." (PMID 34130705, 2021). "Immunohistochemical analyses of the xenograft tumours revealed that the biochanin A and SB590885 combination effectively inhibited the expression of PCNA, a marker of tumour proliferation." (PMID 32774165, 2020). "From the result of the PCNA assay, the MAGE-Au-PFH-NP+laser group exhibited a significant suppression effect on tumor cell proliferation." (PMID 33015175, 2020). "This was apparent in the molecular stratification of samples by mRNA of tumor cells (log-rank PTC = 0.019, HR = 1.5) and tumor-adjacent cells (PTAC = 8.3 × 10−4, HR = 1.8) as well as gene copy number amplifications (PCNA = 9.8 × 10−4, HR = 2.8)." (PMID 32024846, 2020). "Immunohistochemical assays were carried out to evaluate tumor hypoxia (HIF-1α, CAIX) and proliferation (Ki67, PCNA) markers." (PMID 32766135, 2020). "Intriguingly, in our cohort, there was an apparently inverse correlation between tumor size and FAK, EZH2, H3K27me3, and PCNA expression." (PMID 32806748, 2020). "The correlation analysis of THOC1 and proliferation markers PCNA (P < 0.001, r = 0.56) and Ki67 (P < 0.001, r = 0.53) revealed that the expression of THOC1 was positively related to tumor proliferation." (PMID 32669125, 2020). "IHC measurements of proliferating cell nuclear antigen revealed decreased tumor cell proliferation in RaptorECKO tumors, while TUNEL analysis revealed increased tumor cell death." (PMID 32759497, 2020). "PCNA and TUNEL immunohistochemical were used to quantify cell proliferation and apoptosis in tumor sections from all groups." (PMID 33297583, 2020). "Findings indicated that compared with the Lenti-NC group, tumor weights in the Lenti-NDUFA4L2 group were significantly reduced and expression of PCNA in the Lenti-shNDUFA4L2 group was significantly downregulated in OS tissues derived from nude mice." (PMID 33330441, 2020). "Meanwhile, in the tumor-like structures formed by transplanted parental and LGR5+ AM epithelial cells, about 60% of cells co-expressed LGR5 and proliferating cell nuclear antigen (PCNA)." (PMID 32382005, 2020). "CAt extract efficiently reduced PCNA protein expression, indicating that it inhibited HCC tumor cell growth, consistent with the results observed in vitro." (PMID 33050385, 2020).
tumor (continued). "XIAO AI PING was shown to target proliferating cell nuclear antigen (PCNA) and phosphorylated Akt, both markers for tumor growth, and increased levels C/EBP homologous protein (CHOP), a marker for tumor cell apoptosis." (PMID 32372963, 2020). "It is clear that PCNA, CyclinD1, MMP2, and MMP9 are downstream effectors of PI3K/AKT pathway involved in tumor invasion and growth." (PMID 33093458, 2020). "Microscopically, the decrease in PCNA and Ki67 expression were observed in LNT-exposed tumor tissues (the first row)." (PMID 33245358, 2020). "At protein level, we analyzed PCNA and BCL2 as protein markers for tumour proliferation and anti-apoptosis, respectively." (PMID 32251338, 2020). "Curcumin inhibited the expression of PCNA and increased the degree of TUNEL and cleaved caspase-3 staining in tumour tissue." (PMID 31854220, 2020). "All these results suggest that for the BN4-treated system, hypoxia is induced leading to more tumor growth and more angiogenesis (VEGF, HIF-1α, and GRPR) and more cell proliferation (PCNA and Ki67) that leads to enhanced metastasis of tumor cells." (PMID 30887136, 2019). "As compared with CDCP1– cells from muKras tumor cells (DKs5 and HK2-10), the matched CDCP1+ fraction expressed lower levels of markers for cell proliferation, including Ki67, PCNA, and MCM2." (PMID 31461438, 2019). "For each retrieved tumor sample of xenograft, protein expression was evaluated using immunohistochemistry (IHC) with a monoclonal anti-PCNA antibody, CD31 to validate tumor growth inhibition and angiogenesis with 5-FU and shRRAD in xenografts." (PMID 31857616, 2019). "Previous studies showed that both D281G and R248W mutants transactivate expression of tumor progression-related genes such as MYC, PCNA, EGFR, and EGR1; the D281G mutant shows an even greater transactivating activity than R248W in these studies." (PMID 30862120, 2019). "In this study, we identified that decreased expression of TFAM impaired the proliferation of tumour cells by inducing G1/S phase arrest and reducing the expression of E2F1, phospo‐Rb, PCNA and TK1." (PMID 31062473, 2019). "The expression of a proliferation indicator (PCNA) and an anti‐apoptosis protein (BCL‐2) was analysed in each group of tumour tissues." (PMID 31318114, 2019). "A decrease in the proliferating cell nuclear antigen (PCNA) was also observed, indicating the inhibition of tumor cell proliferation by AVA treatment." (PMID 31540249, 2019). "Immunohistochemical analysis revealed that overexpressing miR-330-3p increased PCNA, cyclin D1, CD44 and β-catenin, and reduced cleaved caspase-3 and Bax in tumor tissues." (PMID 31498117, 2019). "Cuc D treatment also showed inhibition of tumor growth in PrCa xenograft mouse model with concomitant decrease in the expression of GLUT1, PCNA and restoration of miR-132." (PMID 30875788, 2019). "Such genes include DNA repair genes (BRCA1, PCNA), a regulator of oxygen homeostasis (HIF1-alpha), anti-apoptotic genes, tumor suppressors, genes of the Akt/mTOR signaling pathway and vascular endothelial growth factor A (VEGFA)." (PMID 31205871, 2019). "NKp44 interacts with the Proliferating Cell Nuclear Antigen (PCNA), which is aberrantly expressed on the surface of tumor cells." (PMID 31736972, 2019). "Taken together, these results demonstrate that hMSCs promote tumor growth through activating MAPK signaling pathway and increasing the expression of proliferation-related proteins, such as Ki-67, pHH3, and PCNA in vivo." (PMID 31142737, 2019). "Compared with the PER2 overexpression group, we observed an increased phenotype in the tumor weight of subcutaneous xenografts formed by oxaliplatin‐treated OSCC cells overexpressing both PER2 and PCNA." (PMID 31728273, 2019). "Consistent with PCNA expression, ERBB2 protein expression shows a significant decrease in tumor tissues of the IT group compared to the INT group (p<0.05)." (PMID 32695310, 2019).
tumor (continued). "Ki-67 and PCNA immunohistochemistry showed that miR-204/211, miR-148a/152 and sh-ANXA2 attenuated the tumor cell growth induced by LncCCAT1." (PMID 31695775, 2019). "IHC staining further confirmed that the expression of Ki-67, a marker of proliferation, was markedly decreased in the tumor tissues from the nude mice transplanted with HepG2.2.15 and HepG2 cells treated with PCNAP1 siRNA or PCNA siRNA." (PMID 31410212, 2019). "Western blot data showed that the protein levels of PCNA, CDK4, CDK6, Cyclin D1, MMP-2, MMP-9, and Bcl-2 were decreased, but cleaved caspase-3 was increased in tumor tissues of ApoE KO mice compared to those of WT mice." (PMID 31275318, 2019). "Consistent with tumor growth inhibition, the result showed that in tumors with depleted LPCAT1 the expression of PCNA, CD34 and MMP9 were diminished (P < 0.05)." (PMID 30791942, 2019). "The mice injected with shHDGF-Ishikawa and shHDGF-RL95-2 cells had smaller tumor burdens and displayed lower expression of HDGF, Ki67 and proliferating cell nuclear antigen (PCNA) in tumor tissues relative to the controls." (PMID 31032220, 2019). "The study also showed that lycopene reduced the expression of proliferating cell nuclear antigen (PCNA) and VEGF in tumor tissues and plasma respectively." (PMID 31600949, 2019). "Hsa_circ_006100 was found to positively regulate PCNA and BCL‐2 levels in the tumour tissues via miR‐195." (PMID 31318114, 2019). "PCNA and FEN1 expression were significantly above tumor average in subtype 2, as were EXO1 and LIG1." (PMID 31857847, 2019). "We also evaluated the expression of proliferative markers, including PCNA and Ki67, to further validate the inhibitory effects of CAP and DDP on OS tumor growth." (PMID 30326933, 2018). "Immunofluorescence staining for PCNA and VEGF in the tumor samples of patients 3 and 8 confirmed the pathology report of disease progression." (PMID 30419021, 2018). "The proliferating cell nuclear antigen (PCNA) is a facilitative element during DNA synthesis during the proliferation and spreading of tumor cells." (PMID 29903985, 2018). "In agreement with the reduction of tumor volume, the significantly decreased expression of POSTN, α-SMA and PCNA, and the apparently increased expression of E-cadherin and cleaved-Caspase-3 were observed." (PMID 30400797, 2018). "Molecular analysis of the tumor tissues showed that melatonin decreased the levels of p-Akt, p-ERK, cyclin D1, PCNA, Bcl-2, Vimentin, Snail, HIF-1α, and VEGF, but upregulated the expressions of Bax and E-cadherin." (PMID 29725496, 2018). "Hepatocytes isolated from HCC tumor tissue and matching paracancerous tissue in CCR10 KO mice showed significantly lower Akt phosphorylation and PCNA expression relative to hepatocytes isolated from their WT counterparts." (PMID 29445190, 2018). "In mouse models, Sal-B markedly inhibited the growth, decreased the PCNA expression, and increased the cell apoptosis of MDA-MB-231 tumor xenografts." (PMID 30555632, 2018). "Proliferating cell nuclear antigen (PCNA) is only found in normal proliferating cells and tumor cells." (PMID 29546069, 2018). "We also detected the proliferation-related molecules (Ki67 and PCNA) and the metastatic-related markers (MMP2 and MMP9) in the xenograft tumor tissues by Immunohistochemical staining." (PMID 30333480, 2018). "Consistent with the tumour growth results, the treatment with Au@PP/RA/siHSP47 plus gemcitabine significantly decreased the percentage of proliferating cell nuclear antigen (PCNA)-positive cells, indicating an effective inhibition of tumour cell proliferation." (PMID 30139933, 2018).
tumor (continued). "The inhibitory effects of KYA1797K on the tumor organoids correlated with the reduction in the β-catenin, pan-RAS, EGFR, and PCNA levels." (PMID 30459318, 2018). "In vivo, hepatocytes isolated from HCC tumor tissue and matching paracancerous tissue in DEN-treated CCR10 KO mice showed significantly lower Akt phosphorylation and PCNA expression relative to WT hepatocytes." (PMID 29445190, 2018). "WB analyses of pooled tumor lysates showed that PC xenografts derived from leptin treated-tumorspheres had significantly higher levels of Notch4, DLL4, JAG1, survivin, PCNA and Oct-4." (PMID 27999190, 2017). "The hazard-ratios for Ki67 and PCNA were 2.5 and 1.8, respectively, for relapse-free survival (RFS) (i.e., tumor recurrence)." (PMID 28978152, 2017). "Consistently, similar results were observed in the staining of proliferating cell nuclear antigen (PCNA), RICTOR and VEGFA in these tumor tissues." (PMID 28030804, 2017). "PCNA, CD31, TUNEL assay, and LC3II staining showed fewer proliferating tumor cells and CD31-positive vessel cells in addition to more dead cells in SB-treated tumor tissues." (PMID 29312612, 2017). "Upregulation of indicated genes as well as the proliferation marker PCNA were validated by qPCR analyses in both 4T1-BALB/c and AT-3/C57BL/6J tumour models." (PMID 28382931, 2017). "In several malignant cells forming tumor nests, FKBP51 and PCNA protein exhibited partial colocalization, also a few stromal cells co-expressed both." (PMID 28441737, 2017). "Meanwhile, downregulation of PCNA (a proliferation marker) and induction of cleaved-PARP (an apoptosis marker) were observed in tumor tissues with PKCζ shRNA or miR-25-5p Therefore, the in vivo signaling changes were in line with the in vitro findings." (PMID 29029434, 2017). "Cell proliferation, as determined by immunocytochemistry, using proliferation antigens Ki-67 and Proliferating Cell Nuclear Antigen (PCNA), is the principal determinant of tumor progression and prognosis." (PMID 29531548, 2017). "Immunostaining and western blot analysis with an anti-proliferating cell nuclear antigen (PCNA) antibody in the C57BL/6 mouse model revealed low PCNA expression and staining in the tumour sections from the rOly-treated group as compared to controls." (PMID 28416764, 2017). "In this feasibility study, several proteins were identified that positively correlated to tumor tissue content including IF6, ARF4, MUC18, UBC12, CSPG4, PCNA, PMEL and MAGD2." (PMID 28445515, 2017). "The results from immunohistochemistry of PCNA and CD31 in tumor tissues are consistent with the tumor apoptosis data." (PMID 28855665, 2017). "IHC analysis showed that protein levels of IKKα/β and the proliferating nuclear cell antigen (PCNA), a marker of proliferation, were significantly decreased in the DHI-treated tumor." (PMID 28906487, 2017). "Before PCNA was described as a ligand for NCR2, it was already reported that its expression inhibits the killing of tumour target cells by NK cells." (PMID 28145491, 2017). "Since the proliferating cell nuclear antigen (PCNA) and cyclin D1 represent two biomarkers of tumor growth, we also evaluated their expression in tumor xenografts." (PMID 28212569, 2017). "Similar protein expression patterns of ACLY, PCNA and Ki-67 were revealed in the GFP positive tumor tissues by IHC staining." (PMID 27317765, 2016). "PCNA (a marker of cell proliferation) and TUNEL assay were used to identify the proliferation ability and apoptosis rate of tumor cells in the xenograft models." (PMID 27922075, 2016). "The slides mounted with tumor tissues were stained with terminal deoxynucleotidyl transferase dUTP nick end labeling (TUNEL), or immunohistochemically stained with anti-Ki67, proliferating cell nuclear antigen (PCNA), phor-Chk1, Ral A or Ral B antibody." (PMID 27741517, 2016). "Since we observed smaller tumor volumes in BME-fed mice, we examined the status of PCNA in tumors to study the mechanism." (PMID 27120805, 2016).
tumor (continued). "In vivo treatment results also showed anti-tumor effcet was most obvious in FA-CD-PLLD/DOC/MMP-9 treated group by analysed tumor volume and PCNA expression." (PMID 27259274, 2016). "In accordance with the reduced tumor volume and weight, the honokiol-treated tumors displayed lower PCNA (proliferating cell nuclear antigen) positive rate." (PMID 27012679, 2016). "The number of PCNA and Ki67 positive cells significantly reduced in the LV-miR-141 and sh-HOTAIR xenograft tumor tissues." (PMID 27121316, 2016). "Extended areas of PCNA-labelled cells were observed in tumor tissues and surrounding tissues in AOM/DSS treated mice; and the PCNA-positive area was substantially lowered by HQD-1 treatment." (PMID 27557503, 2016). "Western blot data showed that SL4 treatment reduced the protein expression of PCNA in MDA-MB-231 xenografts as compared to the control group, suggesting that SL4 retarded tumor growth by inhibiting cell proliferation." (PMID 27819344, 2016). "Accordingly, honokiol dose-dependently inhibited the growth of SAS SP xenograft and markedly reduced the immunohistochemical staining of PCNA and endothelial marker CD31 in the xenograft tumor." (PMID 27012679, 2016). "Further in vivo tumor formation study in nude mice indicated that inhibition of WISP1 delayed the progress of tumor formation and inhibited PCNA expression." (PMID 27409174, 2016). "Overexpression of PCNA in the suprabasal layer of the KCOT can clarify its neoplastic nature and a tendency toward tumor recurrence." (PMID 28357197, 2016). "Results showed that 4-MD effectively suppressed the expression of proliferation marker (Ki-67 and Proliferating cell nuclear antigen (PCNA), ant-apoptotic molecule (Survivin), and therapeutic target molecule (p-STAT3) in tumor tissues." (PMID 26755649, 2016). "GHRH antagonists suppressed cell proliferation and decreased the levels of the proliferation marker, PCNA, in the three cell lines and in PC3 tumor." (PMID 27448980, 2016). "Immunohistochemical staining revealed that the combined rapamycin and KCC009 treatment reduced the cell-proliferation marker proliferating cell nuclear antigen (PCNA), suggesting reduced tumor compared with the single treatments." (PMID 26872016, 2016). "Quantification of PCNA-, γ-H2AX- and TUNEL-positive cells showed that tumor cell proliferation is significantly increased in tumors isolated from Sesn2-/- mice, while DNA damage and apoptosis were not significantly altered by the loss of Sestrin2." (PMID 26913956, 2016). "Because EGFR/PI3K/Akt/mTOR signaling promotes tumor cell proliferation, we next examined the effect of PROG and TMZ on the cell proliferation marker PCNA, which is often used for grading different neoplasms." (PMID 26110872, 2015). "Except for PCNA and CCL4 in tumors, Nampt/PBEF/visfatin expression correlated positively with all, both in normal and tumor colonic tissue." (PMID 26075243, 2015). "We observed reduced blood glucose and serum insulin levels along with decreased proliferating cell nuclear antigen (PCNA) and bromodeoxyuridine positive (BrdU+) tumor cells in 2-DG fed mice." (PMID 26135741, 2015). "The immunohistochemical analysis of tumor sections by H&E and by proliferation antigens against PCNA, cleaved caspase-3 and DR3 staining revealed that tectochrysin inhibited tumor growth." (PMID 26123287, 2015). "However, none of the tumor characteristics were associated with PCNA expression." (PMID 25789021, 2015). "DVDMS combined with multiple focused ultrasound treatments initiated tumor tissue destruction, induced cancer cell apoptosis, inhibited tumor angiogenesis, suppressed cancer cell proliferation, and decreased VEGF and PCNA expression levels." (PMID 26631871, 2015).